APC (APC regulator of Wnt signaling pathway)
Diseases named in the same sentence as APC in open-access papers (continued):
Sharing a sentence is not in itself a finding about the gene and the disease.
adenoma (continued). "The loss of the adenomatous polyposis coli (APC) gene, a regulator of the Wnt/beta-catenin pathway, is considered the initial step of the adenoma-carcinoma sequence and leads to abnormal cell proliferation and the formation of adenomatous polyposis." (PMID 36978108, 2023). "It has been suggested that factors including the development of Adenomatous polyposis coli (APC) mutations were responsible for adenoma initiation in LS patients and that dMMR occurred only after their initiation." (PMID 37162286, 2023). "Testing of multiple adenomas to identify a common somatic mutation via the “adenoma first” approach, has been successfully used to identify APC mosaic variants in adenomatous polyposis." (PMID 37318702, 2023). "It has been supposed that most adenomas arise from an initial loss of the APC gene function, and for that to happen, an epithelial cell must lose the function of both APC alleles." (PMID 35457279, 2022). "In sporadic CRC, cells progress to adenomas by the initial loss of the tumour suppressor adenomatous polyposis coli (APC), which is associated with tumour-elicited inflammation, the disruption of the integrity of the epithelium and adenoma growth." (PMID 35847932, 2022). "The AOM/DSS model of CAC harbors distinct genetic changes compared to conventional sporadic CRC that follows the adenoma-adenocarcinoma sequence, and lacks mutations in APC." (PMID 35658010, 2022). "Inactivating mutations in adenomatous polyposis coli (APC), a well-known tumor suppressor gene, have been demonstrated in more than 70% of adenomas and CRCs." (PMID 35572960, 2022). "Colorectal carcinogenesis is supposed to proceed according to a universally accepted model, in which bi-allelic mutation in the tumor suppressor gene APC occurs as the first event leading from normal mucosa to early adenoma." (PMID 35457279, 2022). "The adenoma from the index of FAP104 showed a truncating APC variant (c.4666dupA, p.Thr1556fs; variant allele frequency (VAF) 23%) and KRAS c." (PMID 36387175, 2022). "FAP results from a germ-line mutation in the adenomatous polyposis coli (APC) gene, a tumor suppressor gene also involved in about 60% of sporadic colorectal carcinomas (CRCs) and adenomas." (PMID 36185899, 2022). "In other work, it has also been demonstrated that a related non-steroidal anti-inflammatory drug, sulindac, inhibited the fission of APC-deficient crypts and thus reduced adenoma numbers in mice." (PMID 35416770, 2022). "Adenomas displayed a higher number of mutations, mainly in APC, compared to serrated polyps (73.1% vs. 47.8%, p = 0.026)." (PMID 35761395, 2022). "Typical manifestations of this pathway are precursor sessile adenoma, wild-type APC (APC-wt), BRAF mutation, characteristic CpG island methylation phenotype, poor differentiation, and mucosa histology." (PMID 35937946, 2022). "In the case of the MSI pathway, adenoma is the result of a simultaneous loss of APC and DNA mismatch repair genes (MMR) failure." (PMID 35884974, 2022). "Alterations in the Wnt pathway are an initial event in the adenoma-carcinoma progression, predominantly due to mutations in the APC (40.3% to 80.0%) followed by the CTNNB1 gene (11.9–20.0%)." (PMID 35761395, 2022). "APC germline mutation will lead to the development of more than 100 adenomas at adolescence that will eventually lead to CRC by the age of 40 if left untreated." (PMID 36531003, 2022).
adenoma (continued). "Mutations in the tumor suppressor gene, APC, triggered changes in the normal intestinal mucosal epithelium to adenoma." (PMID 35709138, 2022). "Most APC-mutation (APC-mt) cancers are assumed to have developed through the classic adenoma-cancer pathway." (PMID 35937946, 2022). "The differences observed were higher frequency of APC mutations in adenomas when compared to serrated sessile lesion and hyperplastic polyp, while variants in BRAF were more prevalent in sessile serrated lesions." (PMID 35761395, 2022). "Because APC truncation underlies most colorectal cancer, drug combinations capable of killing APC-mutant adenoma cells should also be relevant for the treatment of advanced patients with colorectal cancer." (PMID 36860494, 2022). "In the case of JRTs which test positive for the germline APC variant, a diagnosis of adenoma or adenocarcinoma can lead directly to the definitive diagnosis of hereditary GI polyposis." (PMID 36288164, 2022). "Further, CYP26A1, a gene encoding one of the major RA catabolic enzymes, is upregulated in human FAP adenomas and sporadic colon carcinomas that have truncating APC mutations as well as in the intestine of zebrafish apcMCR embryos." (PMID 33987182, 2021). "DNA sequencing analysis of the ten adenoma-adenocarcinoma sample set, revealed seven mutations in the APC gene, six synonymous and one non-synonymous mutation, all of them germline polymorphisms." (PMID 33648461, 2021). "The proportion of APC indels in the MSH3-deficient adenomas was compared with the fraction of APC indels observed among APC variants (somatic and germline) from other sources." (PMID 34843512, 2021). "In MSH3-deficient adenomas, the occurrence of APC indels in a repetitive sequence context was significantly higher than in FAP patients (p < 0.01)." (PMID 34843512, 2021). "Early CRC research indicated that mutations to the APC gene that drive the upregulation of the Wnt pathway are an initiating event that gives rise to the adenoma-carcinoma sequence." (PMID 34458146, 2021). "In sporadic CRC adenomas and adenocarcinomas, APC gene mutations are frequently reported as being nonsense or frame shift mutations that encode for truncated APC proteins." (PMID 34638601, 2021). "The loss of function in the APC gene is commonly associated with the early transformation of normal colon epithelium into adenoma." (PMID 34887764, 2021). "In line with the specific function of MSH3 in the mismatch repair (MMR) system, we identified a characteristic APC mutational pattern in MSH3-deficient adenomas, and confirmed further driver genes for colorectal tumourigenesis." (PMID 34843512, 2021). "An interesting approach would be to compare these data with the impact and spectrum of somatic APC variants in adenomas derived from patients with CMMRD." (PMID 34843512, 2021). "In the vast majority of CRC patients, APC mutation is a central genetic event leading to the ligand-independent activation of the Wnt pathway and the uncontrolled proliferation of adenoma cells." (PMID 34609520, 2021). "Ninety-five percent of patients with familial adenomatous polyposis (FAP) harboring adenomatous polyposis coli (APC) gene mutations develop adenomas by 35 years of age and eventually develop colorectal cancer by age 40–5022." (PMID 34117297, 2021). "APC somatic mutations have been shown to precede other germline gene mutation carriers in CRC or adenomas." (PMID 34549727, 2021). "Conventional adenomas are precursors of the majority of colorectal adenocarcinomas that harbor APC mutations." (PMID 34455522, 2021). "When mutated, the gene that encodes a tumor suppressor, adenomatous polyposis coli (APC), gives rise to traditional adenomas, while the oncogene BRAF, when mutated, gives rise to serrated polyps." (PMID 34452282, 2021).
adenoma (continued). "The genetic sequence dysregulation begins in the intestinal epithelial stem cells by an inactivating mutation of APC allowing the formation of a small adenoma, follows by activation of oncogenes such as KRAS, initiating cancer cell expansion." (PMID 33916891, 2021). "In human CRC, the initial and rate-limiting mutation is the inactivation of APC leading to adenoma formation." (PMID 33671932, 2021). "Loss of function of the tumor suppressor APC, which represses Wnt signaling, is the first step toward adenoma formation." (PMID 34771727, 2021). "This aligns with previous work showing that mRNA levels of CTSB and CTSD increase concurrently with APC gene mutations that initiate the adenoma-adenocarcinoma sequence." (PMID 34428252, 2021). "A key finding of the present study was that almost all (8/9) of the MSH3-deficient adenomas harboured truncating somatic APC variants as the most relevant driver mutation that is supposed to initiate colorectal tumour formation." (PMID 34843512, 2021). "Loss or inactivation of the APC gene on chromosome 5q drives the growth of small adenomas with a hypomethylated genome by promoting clonal expansion." (PMID 34201893, 2021). "Mutations in the APC gene have been found in adenomas and in early stage ampullary adenocarcinomas, identifying this alteration as an early event." (PMID 33922305, 2021). "Contrary to colorectal adenocarcinoma, gastric adenocarcinoma predominantly arises from adenoma precursors and harbors truncating APC mutations, while only a minority of differentiated GCs contain APC mutations." (PMID 34068652, 2021). "Eight of the nine adenomas had truncating somatic variants in APC, and five adenomas had two APC variants." (PMID 34843512, 2021). "Increased crypt fission also underlies “field cancerization” (the emergence, in the non-dysplastic mucosa, of patches of crypts harbouring pro-oncogenic mutations) as well as the eventual formation of adenomas initiated from mouse APC-deficient Lgr5+ ISCs." (PMID 33673710, 2021). "The study provided further evidence about the early onset of ITH in colorectal tumorigenesis, demonstrating that APC-mutant adenomas have polyclonal characteristics with different mutations arising from independent lineages." (PMID 33923068, 2021). "The first event is often a gatekeeping mutation in the adenomatous polyposis coli (APC) gene, which gives the host cell a small growth advantage to slowly develop into a small adenoma." (PMID 32069833, 2020). "According to the multistep genetic model by Fearon and Vogelstein, the APC (adenomatous polyposis) mutation is the first event transforming normal colorectal epithelium to adenoma." (PMID 32917028, 2020). "Custom panel sequencing identified two public mutations in APC (p.E918* and p.R1450*) as well as a private mutation in adenoma region 1 (A1) and cancer region (C) (p.V617F)." (PMID 32895052, 2020). "APC mutation is sufficient to initiate adenoma pathogenesis and no ligand-dependent alterations have been reported in conventional adenomas." (PMID 33202731, 2020). "In many cases, hundreds to thousands of adenomas or adenomatous polyps are formed in CRC patients via an acquired mutation in the adenomatous polyposis coli (APC) gene." (PMID 33195268, 2020). "In stem cell-specific BCL-2 null mice, loss of APC gives rise to significantly fewer adenomas, thus indicating that BCL-2 is crucial for tumor initiation and survival." (PMID 32335811, 2020). "Sample AC6 was re-dissected into two adenoma regions (A1, A2) of different grades and two carcinomas (C1, C3) of different stages, with public mutations of APC, KRAS, and PLK1 found in all four regions." (PMID 32895052, 2020).
adenoma (continued). "APC mutations are found in the earliest microscopic adenomas, and at the same rate in early adenomas as in sporadic tumours." (PMID 33352971, 2020). "The acquisition of an additional APC mutation(s) appears necessary for adenoma development so the occurrence of the additional APC alteration is likely a rate limiting step in CRC development." (PMID 32079164, 2020). "Taken together, these observations fuel the notion that APC loss is the initial driver event for the development of adenomas and subsequent carcinomas." (PMID 32647253, 2020). "(ix) APC mutations lead to increased crypt fission, which is the main mechanism in adenoma morphogenesis." (PMID 33112876, 2020). "Classic FAP patients develop 100s to 1000s of premalignant adenomas which further supports the idea that APC mutations drive tumor growth in vivo." (PMID 32079164, 2020). "Inactivating mutations of the APC gene are considered as the initial step of the adenoma-carcinoma sequence." (PMID 33182693, 2020). "Sample AC9 displayed a hyper-mutated profile with several adenoma- and carcinoma-specific APC missense mutations, along with a public non-sense APC mutation." (PMID 32895052, 2020). "The APC is a hotspot for mutational transformation of Wnt signaling in an active state, resulting in adenoma and adenocarcinoma." (PMID 31003440, 2019). "Eleven somatic mutations were located in genes involved in the early adenoma formation (APC, RNF43 and CTNNB1), whereas two mutations were detected in genes involved in later stages (ARID1A, NRAS)." (PMID 31285513, 2019). "Adenomatous polyposis coli (APC) mutation occurs in as many as 90% of CRCs and causes aberrant activation of Wnt/β-catenin signaling, leading to clonal expansion of ISCs and adenoma formation." (PMID 31362761, 2019). "Hyperplasia and adenoma formation occur also via the loss of APC in cells with normally reduced transcriptional Wnt response." (PMID 30599048, 2019). "Recent sequencing of FAP adenomas have challenged established dogma that APC mutations alone represent the adenoma mutational landscape because recurrent somatic mutations in non-WNT pathway genes were also discovered." (PMID 31231471, 2019). "Previous reports have described enrichment of APC mutation from white blood cells to colonic mucosa and adenomas, confirming the critical role of mosaic mutation in tumorigenesis." (PMID 31269945, 2019). "Mutations in the APC gene with loss of its tumor suppressor activities are crucial to initiate adenoma formation, as described by the bottom-up model." (PMID 31003440, 2019). "As expected, we found that APC was the most frequently mutated gene across the adenomas studied, while other WNT pathway genes (CTNNB1, EP300, TCF7L2, and AMER1) were altered less frequently." (PMID 31781186, 2019). "Inactivating mutations in APC promote gradual development of dysplasia, adenoma, and adenocarcinoma in human cancers and corresponding mouse models." (PMID 31659152, 2019). "An APC gene mutation that leads to epithelial development of adenoma is associated with increased number of ALDH1+ cells and their distribution beyond the crypt." (PMID 29568377, 2018). "The early gene mutations responsible for initial adenoma mutation are represented by APC mutations, and for adenoma enlargement by KRAS and BRAF mutations." (PMID 29652830, 2018).
adenoma (continued). "Somatic inactivating mutations in the adenomatous polyposis coli (APC) gene are believed to be the crucial initiating event triggering adenoma formation, which, over time, can progress to fully malignant carcinomas." (PMID 30150766, 2018). "Colon adenomas and serrated adenomas have the same mutation frequencies, but the genes involved differed substantially, the most mutated genes in conventional adenomas being APC and the most mutated genes in serrated adenomas being BRAF." (PMID 29652830, 2018). "80% of tumors (14 adenomas and 39 carcinomas) harbored at least one mutation in the APC gene, of which more than 60% had incurred a second mutation." (PMID 30256815, 2018). "ADAM10 deletion in APC biallelic loss models markedly reduced adenoma formation both in the small intestine and colon and improved animal survival; activated NOTCH rescued the ADAM10-deficient phenotype." (PMID 29652830, 2018). "Two of these SNPs have been associated with Lynch syndrome and recently the same SNPs (rs16892766 and rs3802842) have been associated with adenoma number in APC mutation carriers causing a more sever FAP phenotype." (PMID 28331556, 2017). "All of this began with the discovery of the APC gene mutation and the presentation of the canonical adenoma-carcinoma sequence." (PMID 28234922, 2017). "APC mutations have frequently been found early in the adenoma-to-carcinoma progression of sporadic CRC." (PMID 28164117, 2017). "Mutations in APC affect the ability of the cell to maintain normal growth and function, which results in cell overgrowth/adenoma formation." (PMID 28331556, 2017). "E1317Q codes for a mutation in the MCR region of the APC gene at β-catenin binding site and this mutation acts like I1307K, by a dominant negative effect on the APC/β-catenin pathway, thus leading to adenoma." (PMID 28576136, 2017). "This is remarkable, considering that it has been shown that APC mutations induce a cytokine-rich pro-proliferative environment in and around adenomas, which should instead promote growth." (PMID 26853366, 2016). "It is assumed that in these patients germline inactivation of one APC allele markedly increases the chance of adenoma formation and that somatic inactivation of the second APC allele is a critical (rate-limiting) event in adenoma formation." (PMID 27279102, 2016). "Of the six FAP adenomas, three had somatic nonsense variants in APC, all falling into the β‐catenin binding domains of APC and distal to the germline APC mutation found in these patients." (PMID 26414517, 2016). "Apc is a negative regulator of the Wnt pathway and loss of APC function results in intestinal hyperproliferation and adenoma formation." (PMID 26956214, 2016). "The majority of CRC is triggered by mutations in adenomatous polyposis coli (APC) gene, which induces the formation of early adenoma." (PMID 27078027, 2016). "In this study we explored the somatic mutational landscape of early‐stage premalignant adenomas from patients with germline mutations in APC and MUTYH as a first step towards defining the catalogue of mutated genes." (PMID 26414517, 2016). "In FAP patients, loss or inactivation of the remaining wild-type APC allele triggers adenoma formation." (PMID 27589228, 2016). "The most prominent signaling pathway in CRC is Wnt signaling, its activation (most frequently by inactivating APC mutations) usually initiates the adenoma-carcinoma sequence and thus colorectal tumorigenesis." (PMID 27713177, 2016).